KRAS (KRas proto-oncogene, GTPase)
Diseases named in the same sentence as KRAS in open-access papers (continued):
Sharing a sentence is not in itself a finding about the gene and the disease.
lung adenocarcinoma (continued). "KRAS mutations, more than 80% of which are G12 mutations, are frequently found in pancreatic ductal adenocarcinoma (> 90%), colorectal adenocarcinoma (> 40%), and lung adenocarcinoma (approximately 30%)." (PMID 37662925, 2023). "KRAS mutation frequency was reported to be 22% in an analysis of 500 lung adenocarcinoma cases." (PMID 37751775, 2023). "This study explored whether the AMG-510 and cisplatin combination increases the anti-tumor effect in lung adenocarcinoma with the mutation of Kirsten rat sarcoma viral oncogene (KRAS) G12C." (PMID 37284902, 2023). "The parallels between the consequences of SETD2 and LKB1 inactivation are all the more provocative given an apparent functional-genetic epistatic relationship in KRAS-driven mouse models and their mutually exclusive pattern of mutation in human of lung adenocarcinoma patients." (PMID 36899051, 2023). "In agreement with a previous, and far more exhaustive analysis of human tumor genomic data, we find that the majority of the human lung adenocarcinomas analyzed had a mutation spectrum favoring a subset of mutations that included the known oncogenic KRAS mutation of the tumor." (PMID 35482806, 2022). "KRAS is the most frequently mutated oncogene in lung adenocarcinomas." (PMID 35703181, 2022). "All KRAS and EGFR mutations were observed in patients with lung adenocarcinoma (5/26 patients each, representing 31.25%) in accordance with previously published data showing KRAS mutations in 18–32% of ADKs and only 1.6–7.1% of SSCs and EGFR mutations in about one-third of ADKs and in 3–18% of SSCs." (PMID 36551569, 2022). "Moreover, BCL6 was highly expressed in human KRAS-mutant lung adenocarcinomas and was associated with poor patient survival." (PMID 36377663, 2022). "About 14% of lung adenocarcinomas have the KRAS G12C mutation." (PMID 36620544, 2022). "Indeed, a better disease-free survival for patients with stage I lung adenocarcinoma harboring G12V/G12C mutations (p=0.0271) was reported, compared with other KRAS mutations." (PMID 35251972, 2022). "New phase I, II, and III clinical trials using targeted inhibitors for the specific glycine-to-cysteine mutation at codon 12 (KRAS c.34G>T/KRAS G12C) of the KRAS gene showed promising results in approximately 30% of lung adenocarcinomas harboring a KRAS G12C mutation." (PMID 35205778, 2022). "Activating mutations in KRAS occur in 32% of lung adenocarcinomas (LUAD)." (PMID 36163168, 2022). "A link between KRAS mutations and IKKα has been observed in lung adenocarcinoma development." (PMID 35173303, 2022). "Our cases not only confirm various claims made by earlier studies regarding KRAS G12C mutations but also present the first documentation highlighting and describing the cases of KRAS G12C-mutant lung adenocarcinoma in patients, which have been possibly missing because of a lack of research." (PMID 36004014, 2022). "As over one-third of lung adenocarcinomas harbour KRAS mutations, KRAS is therefore an important biomarker that might be used in monitoring treatment, as a biomarker for relapse/progression (disease monitoring), and as a prognostic biomarker." (PMID 36386815, 2022). "KRAS mutations were identified in 158 lung adenocarcinoma samples, of which 147 (93%) could be identified using the Idylla KRAS cartridge." (PMID 35627184, 2022). "We thus demonstrate the prognostic value of RAG classification and RI quantification in 500+ lung adenocarcinoma patients from two independent cohorts, benchmarked against the failure of KRAS mutational status or previous RAS signatures to predict patient outcomes." (PMID 36163168, 2022). "Interestingly, STK11 deletion seems to drive lineage transformation to squamous-cell carcinoma in KRAS mutated lung adenocarcinoma." (PMID 35251972, 2022).
lung adenocarcinoma (continued). "PD-L1 expression in KRAS-mutated lung adenocarcinomas from the two cohorts combined." (PMID 35562908, 2022). "KRAS G12C transversion mutations account for 41% of KRAS mutations and are almost exclusively detected in lung adenocarcinoma, with a nearly 90% incidence rate in smokers, which is consistent with our findings wherein both patients who reported their smoking status were smokers." (PMID 36004014, 2022). "Pathology results indicated a KRAS-mutated lung adenocarcinoma." (PMID 36290858, 2022). "EGFR and KRAS are the most frequently mutated oncogenes in human lung adenocarcinoma." (PMID 35368709, 2022). "In addition, further developments are warranted to identify selective agents against KRAS G12D and G12V mutations, representing 38% of all KRAS-mutant lung adenocarcinomas." (PMID 36012655, 2022). "Notably, the oncogenic driver mutations, such as EGFR and KRAS, are commonly observed in lung adenocarcinoma." (PMID 34884633, 2021). "Furthermore, in smokers with KRAS mutation, lung adenocarcinoma STAT3 correlated with poor survival and advanced malignancy." (PMID 34047814, 2021). "Moreover, our findings in lung adenocarcinoma patients suggest that increased oncogenic KRAS is associated with increased activation of pAMPK in LKB1 mutant patients." (PMID 33514834, 2021). "It has been found that high PD-L1 expression was significantly correlated with the presence of KRAS mutations in pulmonary sarcomatous carcinoma and lung adenocarcinoma, indicating that patients with KRAS mutations may exhibit a more efficient response to ICB." (PMID 34301278, 2021). "This is possible when the SMARCA4 in a KRAS-dependent lung adenocarcinoma is a missense mutation, identified through an intact BRG1 expression or the loss of BRG1 expression caused by a nonsense, frameshift, or splice site mutation in the SMARCA4 gene in a KRAS-independent lung adenocarcinoma." (PMID 34440689, 2021). "In addition, SLC7A11, a cystine/glutamate antiporter that specifically uptakes cystine, was overexpressed in patients with KRAS-mutated lung adenocarcinoma and positively associated with tumor progression." (PMID 34502181, 2021). "However, intriguingly, KRAS mutation can dictate a different immune environment in other types of adenocarcinoma, such as colorectal adenocarcinoma and lung adenocarcinoma." (PMID 34069772, 2021). "However, co-occurring genomic alterations are reported in up to 50% of KRAS-mutated lung adenocarcinomas." (PMID 34944952, 2021). "focused on indirect targeting of KRAS in a co-mutation setting in lung adenocarcinoma (LUAD)." (PMID 34781949, 2021). "Inhibition of SLC7A11 leads to poor prognosis in KRAS-mutated lung adenocarcinoma." (PMID 34630529, 2021). "Taken together, our data suggest that the loss of the WT allele in KRAS mutant lung adenocarcinomas is often associated with G12C and G12V mutations, and the loss of the WT copy of the KRAS gene modulates response to treatment with compounds targeting KRAS downstream substrates." (PMID 34573384, 2021).
lung adenocarcinoma (continued). "Notably, aberrant mutations of EGFR, BRAF, or KRAS occurred in lung adenocarcinomas in a mutually exclusive manner." (PMID 34884633, 2021). "Taken together, these data suggest that activation of FoxM1 is increased in KRAS mutant lung adenocarcinomas retaining the WT KRAS allele and that downregulation of its transcriptional activity may represent a therapeutic target for this group of patients." (PMID 34573384, 2021). "It is interesting to note that among the top ~50% of SDC1 and among which the top 20% CASP4 high-expressing lung adenocarcinoma and colon cancer patients (out of 503 for lung and 524 for colon, respectively), approximately 20 (lung) and 50 (colon)% of them possess KRAS mutations." (PMID 33452234, 2021). "An activating KRAS mutation occurs in approximately 30% of lung adenocarcinomas." (PMID 35201504, 2021). "To test whether AMPK signaling may be involved in human KRAS/LKB1 mutant lung adenocarcinoma we performed a correlation analysis between pAMPK and oncogenic codon 12 KRAS mRNA for LKB1 loss-of-function and LKB1 wild-type patients using TCGA data." (PMID 33514834, 2021). "In addition, we used data from TCGA to show that putative inactivating NOTCH1 mutations co-occur with KRAS mutations and genomic amplifications in lung adenocarcinomas." (PMID 34257546, 2021). "In addition to PDAC, other cancers in humans, such as colorectal adenocarcinomas (CRACs) and lung adenocarcinomas (LUACs), also harbor a high prevalence of KRAS mutations." (PMID 34069772, 2021). "Furthermore, KRAS mutation is a recently highlighted mutation, and KRAS inhibitor (AMG510) has shown antitumor activity in one case of partial response and two cases of stable disease among six patients with previously treated KRAS‐mutated lung adenocarcinoma." (PMID 33960703, 2021). "KRAS mutations occur in 31% of unresected treatment naïve lung adenocarcinomas." (PMID 34944952, 2021). "Furthermore, the treatment of KRAS-mutated lung adenocarcinoma with HG106 in several preclinical lung cancer mouse models resulted in marked tumor suppression and prolonged survival." (PMID 34502181, 2021). "Thus, loss of the WT allele in KRAS mutant lung adenocarcinomas and its effect on tumor invasiveness and metastasization should be evaluated in future investigations." (PMID 34573384, 2021). "The Kirsten Rat Sarcoma (KRAS) mutation is the commonest oncogenic drive mutation in lung adenocarcinoma (LUAD) and immunotherapy may be quite promising for KRAS-mutant LUAD." (PMID 33072585, 2020). "This suggested that, compared to Caucasians, there may be differences in the frequency of KRAS mutations in lung adenocarcinoma harbored different mucinous content in East-Asians." (PMID 33505917, 2020). "In patients with lung adenocarcinoma, approximately 13% harbor a mutation of KRAS G12C." (PMID 32560187, 2020). "However, this is hard to generalize because the number of KRAS mutated lung adenocarcinoma is much smaller (n = 6) than EGFR mutated adenocarcinoma (n = 15) in this study cohort." (PMID 32196518, 2020). "Activating KRAS mutation rate is around 10–30% in human lung adenocarcinoma." (PMID 33276627, 2020). "Lower than expected variant allele frequency of IDH1/2 mutants and coexistence of IDH1/2 mutations with known trunk drivers in the BRAF, EGFR, and KRAS genes suggest they could be branching drivers leading to subclonal evolution in lung adenocarcinomas." (PMID 32333643, 2020).
lung adenocarcinoma (continued). "The KRAS G12C mutation accounts for about 14% of lung adenocarcinoma." (PMID 32448366, 2020). "Almost 30% patients with lung adenocarcinoma are positive for KRAS gene mutation." (PMID 32206449, 2020). "Few studies have investigated conventional CT features and KRAS mutations in lung adenocarcinoma." (PMID 31783917, 2019). "We observed KRAS mutations in 20.4% of lung adenocarcinomas." (PMID 30824880, 2019). "KRAS mutations induce PD-L1 expression through p-ERK signaling in lung adenocarcinomas." (PMID 31775797, 2019). "However, only a few studies have examined the correlation between the CT findings of lung adenocarcinoma and KRAS mutational status." (PMID 31783917, 2019). "Approximately 15–25% of patients with lung adenocarcinoma have tumour-associated KRAS mutations." (PMID 30953094, 2019). "However, the EGFR mutation frequencies in East Asian lung adenocarcinoma were higher than previously reported in USA/Europe patients, whereas the overall frequency of KRAS mutations was much lower than in the West instead." (PMID 31749831, 2019). "Thus, we investigated the frequency of EGFR and KRAS mutations in a large Brazilian series of lung adenocarcinoma together with patients’ genetic ancestry, clinicopathological and sociodemographic characteristics." (PMID 30824880, 2019). "In lung adenocarcinomas there is a trend toward co-mutation of KRAS and KEAP1." (PMID 31581742, 2019). "KEAP1 deletion or mutation is frequently found in KRAS-driven lung adenocarcinomas and may present an obstacle to ERK inhibitor therapy in these tumors." (PMID 31439014, 2019). "Four out of five treated patients with concordant KRAS G12 mutations were lung adenocarcinoma, suggesting KRAS dependency in every cancer cell, which may suggest KRAS-dependent therapeutic vulnerabilities in these tumors." (PMID 31546879, 2019). "KRAS mutations in lung adenocarcinoma have special pathological features." (PMID 31783917, 2019). "We hypothesized that DESCT features can be used to distinguish KRAS mutations from EGFR mutations in lung adenocarcinoma." (PMID 31783917, 2019). "However, in a cohort of 482 lung adenocarcinomas, it was demonstrated that KRAS mutations do occur in patients with lung adenocarcinomas without a smoking history, but the mutations are different." (PMID 29868480, 2018). "Other genetic alterations cooperate with KRAS mutation in the development of lung adenocarcinomas." (PMID 30060526, 2018). "In support of this hypothesis, it has been documented that apatinib therapy can evoke stable disease response in advanced lung adenocarcinoma patients with KRAS mutation." (PMID 30263099, 2018). "We also identify negative associations (odds ratio < 1) between mutational signatures and driver mutations, and here we examine the role of aging and cigarette smoke mutagenesis in the generation of driver mutations in IDH1 and KRAS in brain cancers and lung adenocarcinomas respectively." (PMID 30412573, 2018). "For lung adenocarcinoma and endometrial carcinoma, we observed a cross-cancer effect for KRAS/NRAS-mutated cases as ATM levels are decreased, and MAPK_pT202_Y204, Claudin-7, S6_pS235_S236, and MEK1_pS217_S221 are increased in both histological tumor types consistently." (PMID 30442178, 2018).
lung adenocarcinoma (continued). "Thus, it appears that the high frequency of this KRAS mutation compared with others in lung adenocarcinoma is, potentially, owing to both smoking-associated mutational processes and the intrinsic selective advantage of the mutation." (PMID 29748584, 2018). "Furthermore, in lung adenocarcinoma, it has been demonstrated that KRAS mutation induces the expression of programmed death ligand 1 (PD-L1)." (PMID 29992354, 2018). "Importantly, simultaneous LKB1 and KRAS mutations in lung adenocarcinoma cell lines were previously shown to prevent MYC downregulation and sensitivity in response to BET inhibition." (PMID 29721157, 2018). "We also tried to explore whether blocking the PD-1/PD-L1 axis could be a novel therapeutic option for lung adenocarcinoma with KRAS mutation." (PMID 28451792, 2017). "Interestingly, no mutations were identified in EGFR gene that together with KRAS is the most commonly mutated gene in lung adenocarcinoma." (PMID 28194229, 2017). "KRAS mutations maybe the most frequent gene abnormalities in lung adenocarcinoma since about 3% to 8% of Chinese patients and 15% to 25% of Caucasian patients were KRAS mutations positive." (PMID 29285248, 2017). "The results implied that PD-L1 expression was associated with KRAS mutation in lung adenocarcinoma." (PMID 28451792, 2017). "Our study demonstrated that KRAS mutation could induce PD-L1 expression through p-ERK signaling in lung adenocarcinoma." (PMID 28451792, 2017). "We show the clinical data that indicate that KRAS mutations are frequent in European patients with MPE from lung adenocarcinoma and that they might be underappreciated." (PMID 28508873, 2017). "To better understand how the mutation status of KRAS influences survival signaling in cancer cells, we utilized data obtained from gene expression profiling of mouse KRAS G12D-induced lung adenocarcinomas and control untransformed cells, which we previously reported." (PMID 28152508, 2017). "Furthermore, whereas KRASG12C is the most frequent KRAS mutation in lung adenocarcinomas in current/former-smokers, it is approximately three times less prevalent in never-smokers in which KRASG12D is the dominant mutation 45,58,59." (PMID 29233960, 2017). "Similarly, KRAS mutations are present at 60% lower frequency in Indian lung adenocarcinoma patients than compared with the Caucasian population." (PMID 27998968, 2017). "However, Pelosi and co-workers found significant intra-tumour heterogeneity including co-existence of EGFR and KRAS mutations in minority clones using laser microdissection of multiple areas in lung adenocarcinomas." (PMID 28347348, 2017). "We transduced OCT3/4, SOX2, and KLF4 (hereafter, OSK) or EGFP into a KRAS-mutated (G12S) human lung adenocarcinoma cell line (A549) using retrovirus vectors, then cultured the cells in 10% fetal bovine serum (FBS) containing Dulbecco’s modified Eagle’s medium (DMEM)." (PMID 28951614, 2017). "Interestingly, studies have found that the presence of driver genes, including EGFR and KRAS, are often associated with pathological subtypes in lung adenocarcinomas." (PMID 29137260, 2017). "In lung adenocarcinoma, oncogenic KRAS mutations are highly prevalent (~25 %) but therapy choices are very limited indicating that our findings might be of relevance to improve treatment of a significant fraction of lung adenocarcinoma patients." (PMID 26895954, 2016). "Thus the effect of mutational activation of KRAS on guanine-nucleotide exchange factors for small GTP-binding proteins is broader in lung adenocarcinoma than its biochemical activation of exchange factors that activate Ral proteins." (PMID 27301828, 2016). "For example, lung adenocarcinomas that contain the KRAS mutation may exhibit increased expression of PDL1, compared to wild-type tumors that do not harbor the KRAS mutation." (PMID 27854240, 2016).